RIPK1 (receptor interacting serine/threonine kinase 1)
Diseases named in the same sentence as RIPK1 in open-access papers (continued):
Sharing a sentence is not in itself a finding about the gene and the disease.
Sepsis (continued). "This study underscores the pivotal role of necroptosis in the pathophysiology of sepsis, as reflected by elevated levels of RIPK1, IL-1β, and IL-18 and reduced expression of caspase-8 across both pediatric and adult patients." (PMID 40722817, 2025). "To specifically map the cellular sites of RIPK1 activation during sepsis pathogenesis, we performed multiplex immunofluorescence staining on lung sections from CLP model mice." (PMID 40953301, 2025). "This temporal sequence—RIPK1 activation preceding tissue damage—establishes RIPK1 as an upstream driver of pathological signaling in sepsis‐induced lung injury." (PMID 40953301, 2025). "In summary, our results indicate that compound 62 mitigates sepsis‐induced lung injury by targeting RIPK1‐mediated inflammatory cascades." (PMID 40953301, 2025). "Taken together, these findings provide robust evidence that the inhibition of RIPK1 kinase activity substantially mitigates acute pulmonary pathological alterations induced by sepsis." (PMID 40953301, 2025). "In conclusion, this study repositions RIPK1 as a pleiotropic regulator of sepsis‐induced lung injury, bridging necroptosis, and chemokine‐driven inflammation." (PMID 40953301, 2025). "In summary, ECG protects sepsis induced ALI mice by inhibiting necroptosis mediated by the ZBP1/MLKL/RIPK1 signaling pathway." (PMID 41496909, 2025). "In this study, selective activation of RIPK1 in type II alveolar epithelial cells (AECs) is observed during sepsis." (PMID 40953301, 2025). "This evidence suggests that either genetic or pharmacological inhibition of RIPK1 can prevent TNF-induced sepsis." (PMID 40007541, 2025). "To further explore the role of alveolar epithelial cell RIPK1 in sepsis‐induced lung injury, we carried out a gene knockdown experiment using a recombinant adeno‐associated virus (rAAV) system delivered through intratracheal instillation." (PMID 40953301, 2025). "RIPK1 has been reported to be involved in the progression of various diseases, including colitis, psoriasis, sepsis, viral infections, neurodegenerative diseases, graft vs host disease, lung injury, and atherosclerosis." (PMID 38521771, 2024). "Nevertheless, both of them confirmed that RIPK1 kinase activity is essential for the survival of animals subjected to sepsis." (PMID 38816685, 2024). "Despite the growing interest in sepsis models that focus on necroptosis or downstream regulators, the upstream pathways that regulate RIPK1 and its modifications have received comparatively less attention." (PMID 37090690, 2023). "In this paper, we introduce the regulation of RIPK1, RIPK1 PANoptosome’s role in Inflammatory and sepsis, and perspectives." (PMID 37090690, 2023). "Given the exploration of RIPK1 in rheumatoid immune diseases and inflammatory reactions, there have been studies using RIPK1 inhibitors to regulate the inflammatory response in sepsis." (PMID 37090690, 2023). "The treatment of systemic inflammatory response syndrome (SIRS) and sepsis is interesting given the molecular function of RIPK1 in sepsis." (PMID 38129399, 2023). "Fortunately, there has been a growing body of research aimed at exploring the role of RIPK1 in regulating the inflammatory response in sepsis." (PMID 37090690, 2023). "In murine sepsis, RIPK1 has been shown to induce the production of GM-CSF, IL-6, IL-8, and TNF under LPS stimulation, implying that RIPK1 has a detrimental impact on sepsis." (PMID 38001795, 2023). "For the treatment of diseases in which dysregulation of necroptosis occurs, such as neurodegenerative diseases, sepsis, and cancer, RIPK1 serine 331 O-GlcNAcylation warrants further study as a useful therapeutic target or strategy." (PMID 37359541, 2023). "For instance, the RIPK1 inhibitor Nec-1 can reduce renal ischemia and reperfusion injury as well as sepsis-related acute kidney injury." (PMID 37954576, 2023).
Sepsis (continued). "This manuscript centers on the impact of RIPK1 regulation induced by sepsis on the inflammatory response, and the current state of medical research." (PMID 37090690, 2023). "Previous clinical studies have primarily focused on measuring the concentration of serum RIPK1, providing a reference for predicting the occurrence and development of sepsis." (PMID 37090690, 2023). "The study highlighted the clinical relevance of RIPK1 kinase inhibition in sepsis and revealed the possibility of targeting RIPK1 in the programmed necrosis pathway as a potential therapeutic target for SIRS and sepsis." (PMID 36249746, 2022). "TNFα-induced systemic inflammatory response syndrome (SIRS) is an animal model of sepsis, which involves both RIPK1-dependent apoptosis and necroptosis." (PMID 34075030, 2021). "Recent studies examining the necroptosis regulators of RIPK1, RIPK3, and MLKL in patients with sepsis reported that their levels were associated with disease severity and/or mortality." (PMID 32492832, 2020). "This is a sterile model of sepsis that depends on RIPK1 kinase activity and RIPK3.42, 43 Sorafenib, administered by gavage 1.5 h before i.v. mTNF treatment, significantly protected mice from hypothermia and death caused by mTNF in a dose-dependent manner." (PMID 28661484, 2017). "Targeting a potential RIPK1-GSDMD pathway could offer new therapeutic strategies for conditions characterized by excessive cytokine release such as sepsis, auto-immune disease, or inflammatory cancers." (PMID 41596270, 2026). "Beyond bacterial sepsis, exploring RIPK1's role in viral or fungal models could elucidate its universality across sepsis etiologies." (PMID 40953301, 2025). "Furthermore, the development of compound 62, a selective RIPK1 inhibitor with improved pharmacokinetics, addresses a critical gap in sepsis therapeutics." (PMID 40953301, 2025). "Clinically, this study suggests that RIPK1 kinase inhibitors may offer benefits for patients with shock and/or sepsis, particularly in preserving vascular integrity and preventing tissue damage." (PMID 40007541, 2025). "This article examines the central role of RIPK1 in the pathogenesis of sepsis‐induced lung injury." (PMID 40953301, 2025). "Interventional trials using RIPK1 inhibitors or caspase-8 modulators could test the therapeutic potential of modulating cell death pathways in sepsis." (PMID 40722817, 2025). "This survival benefit was associated with attenuated lung pathology, including reduced alveolar hemorrhage and leukocyte infiltration, and preserved ATII cell populations, underscoring the pivotal role of epithelial RIPK1 in driving lethal inflammation during sepsis." (PMID 40953301, 2025). "Notably, inhibition of the RIPK1 kinase has shown significant promise in providing robust and consistent protection against sepsis, mitigating sepsis-induced hypothermia and preventing its lethality." (PMID 40456737, 2025). "It’s reported that the inhibition of RIPK3 or RIPK1 could reduce systemic inflammation and organ damage in newborn mice with sepsis." (PMID 37091800, 2023). "Though necroptosis was initially posited as a driver of multiple inflammatory pathologies, including sepsis, evidence of widespread necroptosis in septic humans is lacking, and the hope of limiting septic inflammation by narrowly targeting the RIPK1 or RIPK3 kinase domain is likely misplaced." (PMID 38274794, 2023). "Developing highly selective inhibitors that target RIPK1 may offer innovative solutions for treating a broad range of diseases, including neurological disorders, inflammatory diseases, tumors, and sepsis." (PMID 37954576, 2023). "Consequently, the role of RIPK1 kinase activity in the systemic inflammatory response and sepsis has garnered increased attention." (PMID 37090690, 2023). "This provides further evidence that necroptosis plays a significant role in the pathophysiology of sepsis and suggests that RIPK1-dependent necroptosis may be a potential novel therapy target in sepsis." (PMID 36765040, 2023).
Sepsis (continued). "With respect to the critical roles of RIPK1 in inflammation, RIPK1 has been identified as a therapeutic target of monogenic and polygenic autoimmune, inflammatory, neurodegenerative, ischemic and acute conditions, such as sepsis, by the potential applications of RIPK1 inhibitors." (PMID 34861878, 2021). "Finally, investigating RIPK1's contribution to chronic sequelae, such as post‐sepsis fibrosis and immune disorder, may uncover broader implications for critical care outcomes." (PMID 40953301, 2025). "Necroptosis effector genes are markedly upregulated with increased RIPK1, RIPK3, and MLKL co-expression evident in spinal GABAergic neurons, while administration of the necroptosis inhibitor Necrostatin-1 substantially preserves neurons and reverses sepsis-associated cardiac functional changes." (PMID 40692211, 2025). "Thus, studies examining the regulation of RIPK1 may hopefully provide a better understanding of the mechanism of sepsis and directions for the treatment of sepsis in the future." (PMID 37090690, 2023). "Consequently, the equilibrium between RIPK1′s pro-survival functions and the activation of its pro-death kinase activity may influence the clinical outcome during different stages of sepsis." (PMID 38001795, 2023). "Taken together, these results showed RIPK1 as a key driver of ATII cell injury and sepsis‐induced lung injury." (PMID 40953301, 2025). "RIPK-1 and RIPK-3, key mediators of the necroptosis pathway, were elevated in patients with sepsis across both age groups, with RIPK-1 reaching statistical significance (p < 0.001)." (PMID 40722817, 2025). "In sepsis, cytoplasmic DUBs (CYLD and A20) ubiquitylize the K63 chain of key proteins, such as RIPK1 and NEMO, by removing the inhibit overactivation of NF-κB and MAPK signaling, thereby reducing cytokine release and inflammatory spread." (PMID 39720715, 2024). "In this study, we also found that RIPK1 and RIPK3, which are key proteins involved in necroptosis, were significantly upregulated in patients with sepsis and septic shock." (PMID 37475188, 2023). "Given the complex array of potential signaling outcomes downstream of RIPK1 and RIPK3, the understanding of their role in sepsis remains incomplete and is actively evolving." (PMID 38274794, 2023). "In conclusion, linifanib inhibited RIPK1-dependent necroptosis and attenuated SIRS-induced sepsis, providing the first preclinical data supporting repurposing linifanib to reduce mortality from sepsis." (PMID 36765040, 2023). "However, the mechanism regulating RIPK1 in sepsis remains unclear." (PMID 37090690, 2023). "Previous studies have demonstrated that that the classical pathway of necroptosis, RIPK1/RIPK3 pathway, can collaborate with the key protein of pyroptosis, GSDMD, to amplify inflammatory signals and exacerbate tissue damage during sepsis." (PMID 38161332, 2023). "We found significantly higher expression of RIPK1, RIPK3, and MLKL in the peripheral blood nucleated cells of sepsis patients than controls." (PMID 36765040, 2023). "Furthermore, RIPK1-dependent necroinflammation, independent of necroptosis, has been implicated in various human pathologies, including hepatic and renal diseases as well as sepsis." (PMID 33273695, 2021). "Among the included sepsis patients, the primary infection sites, the concurrent chronic diseases, and the regulated proteins of necroptosis including RIPK3 and RIPK1 levels were prospectively collected." (PMID 29137405, 2017). "Importantly, necroptosis mediated by RIPK1 and RIPK3 significantly contributes to the increased mortality observed during sepsis." (PMID 40817040, 2025). "Additionally, necrostatin-1 (Nec-1), a RIPK1 inhibitor, effectively suppresses necroptosis, showing therapeutic promise in fatal systemic inflammatory response syndrome (SIRS) and sepsis." (PMID 40817040, 2025). "Previous studies have suggested that serum RIPK1 does not differ significantly in relation to the severity of sepsis." (PMID 37090690, 2023).
Sepsis (continued). "Subsequent research has focused more on differences in indicators such as RIPK3 and MLKL, but this does not necessarily indicate that inhibition of RIPK1 is ineffective in treating sepsis." (PMID 37090690, 2023). "In an LPS-induced septic piglet model, inhibition of RIPK1 attenuated intestinal epithelial injury, accompanied by an increase in the level of MLKL phosphorylation, suggesting that necroptosis affects intestinal epithelial cell death during sepsis." (PMID 37090690, 2023). "While RIPK3 levels in sepsis patients as well as the RIPK1 levels in sepsis, severe sepsis, and septic shock patients did not remarkably change within 120 hours." (PMID 29137405, 2017). "Our research results demonstrate that ECG alleviates sepsis-induced ALI by inhibiting the NLRP3/Caspase-1/GSDMD signaling pathway-mediated pyroptosis, the Bcl-2/Bax/Caspase-3 signaling pathway-mediated apoptosis, and regulating the ZBP1/MLKL/RIPK1 signaling pathway-mediated necroptosis." (PMID 41496909, 2025). "This epithelial‐specific regulation mechanistically links RIPK1 to neutrophil‐mediated injury and positions RIPK1 as a critical orchestrator of CXCL1‐driven neutrophilic inflammation, highlighting its unique role in translating epithelial stress signals into alveolar injury during sepsis." (PMID 40953301, 2025). "In this study, we hypothesize that RIPK1 activation in type II alveolar epithelial cells (ATII) promotes CXCL1‐driven neutrophil recruitment via JAK1‐STAT3 signaling, independently of necroptosis, thereby exacerbating sepsis‐induced lung injury." (PMID 40953301, 2025). "In addition, the markers of necroptosis RIPK1, RIRK3, and MLKL and the HMGB1 released by necroptosis in peripheral blood of septic patients were significantly increased and positively correlated with the severity and mortality attributed to sepsis." (PMID 38816685, 2024). "In sepsis, the persistence of DAMP and PAMP contributes to an uncontrolled inflammatory response, in which ubiquitination and deubiquitination mechanisms finely regulate inflammatory intensity and cell survival by modulating key signaling molecules (e.g., RIPK1, NF-κB)." (PMID 39720715, 2024). "However, cohorts of septic patients do display increased expression of RIPK1, RIPK3 and MLKL, implying these mediators may be involved in sepsis progression." (PMID 38274794, 2023). "The effect of treatments targeting RIPK1 on the development of sepsis has not been clarified." (PMID 37090690, 2023). "While targeting the kinase activity of RIPK1 could potentially limit the rapid escalation of inflammation, such an intervention did not consistently meet treatment expectations when sepsis was complicated and intracellular homeostasis was dynamically changing." (PMID 38001795, 2023). "Therefore, RIPK1 may not be suitable for determining the severity of sepsis." (PMID 37090690, 2023). "The RIPK3 levels in severe sepsis and septic shock group were markedly higher than those in sepsis group at various time points (all p < 0.05), and trends were remarkably similar for SOFA scores, CRP levels, and PCT among these groups but not RIPK1 levels and WBC counts." (PMID 29137405, 2017).
colitis (37 papers, 2017 to 2025). Inflammation of the colon. "For instance, mice with intestinal epithelial cell-specific RIPK1 deficiency develop colitis and show disrupted tissue architecture due to increased epithelial cell death, suggesting that RIPK1 has a protective role in regulating gut epithelial homeostasis." (PMID 41019071, 2025). "In dextran sulfate sodium-induced colitis mice, OTUD1 binds to RIPK1, removing K63-linked polyubiquitination and inhibiting NF-κB activation, reducing pro-inflammatory cytokines and preventing colitis." (PMID 40500776, 2025). "We found that DC-specific deletion of RIPK1 caused FADD-dependent spontaneous colonic inflammation characterized by increased neutrophil and Ly6C+ monocytes." (PMID 34462571, 2022). "Mutations in RIPK1 should be considered in very young patients presenting with colitis and perianal fistulas." (PMID 36466854, 2022). "Despite the elevated basal colonic inflammation, loss of RIPK1 in DCs surprisingly rendered mice resistant to injury-induced colitis." (PMID 34462571, 2022). "Colitis in both the FaddVillin.cre and Caspase-8Villin.cre mice is caused by RIPK1 kinase activity-dependent IEC necroptosis and is primarily mediated by TNFR1, with a minor role for ZBP1." (PMID 33924766, 2021). "The authors showed that in acute DSS-induced colitis, treatment of mice with the RIPK1 inhibitor necrostatin-1 triggered anti-inflammatory and antitumorigenic effects that attenuated intestinal inflammation and colitis-associated tumor growth in mice." (PMID 29560122, 2018). "In addition, in DSS-induced colitis, the DJ-1 deficiency-induced activation of p-RIPK1, p-RIPK3 and p-MLKL was dramatically blunted in the DKO mice." (PMID 40877233, 2025). "As a result, patients who are extremely young and diagnosed with fistula-in-ano and colitis should be checked for RIPK1 mutations, implying that mutations of RIPK1 may also lead to the development of IBD." (PMID 39118979, 2024). "Sensing of endogenous Z-DNA by ZBP1 has been shown to induce skin inflammation in mice with epidermis-specific RIPK1 knockout and colitis in mice with intestinal epithelial-specific FADD knockout." (PMID 41488643, 2025). "Mice with myeloid cell specific TBK1 and IKKε inhibition showed ileitis and colitis that were almost completely inhibited by homozygous expression of kinase-inactive RIPK1." (PMID 38167258, 2024). "In other studies, Lu and team found that RIPK1 inhibitors prevent colitis by reducing the infiltration of immunocytes in the lamina propria." (PMID 39118979, 2024). "Blocking RIPK1 by Nec-1s in vivo and in vitro dramatically alleviated the colitis and cell death which shares the same phenotype with ABIN1 overexpression." (PMID 36034412, 2022). "Nec-1s, a RIPK1 inhibitor which plays a potent role in anti-inflammatory, was subjected to investigate the relationship between ABIN1 and RIPK1 in the DSS-induced colitis model." (PMID 36034412, 2022). "ZBP1 binding with ERV-derived dsRNA activates embryonic lethality in RIPK1−/− mice and colitis in RIPK1−/− IECs, and binding with leaked mtDNA leads to chronic oxidative stress-induced ocular pathologies." (PMID 36142136, 2022). "Collectively, these results indicate that DC-specific RIPK1 deletion confers the protection against DSS-induced colitis in a FADD-dependent but RIPK3-MLKL-independent manner." (PMID 34462571, 2022). "To examine how this basal colonic immune dysregulation by DC-specific RIPK1 deletion affects development of colitis, we challenged the mice with dextran sulfate sodium (DSS), which induces acute damage of colonic epithelial cells and colitis-like inflammation." (PMID 34462571, 2022). "Different groups have also reported that overexpression of A20 in IECs is protective in lipopolysaccharide (LPS) and DSS-induced colitis models but promotes RIPK1-dependent IEC death in response to TNF." (PMID 33924766, 2021).